STAT3 (signal transducer and activator of transcription 3)
Diseases named in the same sentence as STAT3 in open-access papers (continued):
Sharing a sentence is not in itself a finding about the gene and the disease.
cancer (continued). "Second, our data showed ERK or STAT3 activation after PI3K inhibition alone in KRAS mutant cancer cell lines as a previous study showed that inhibition of mTORC1 induces RAS pathway as well." (PMID 22159814, 2012). "The involvement of STAT3 in tumorigenesis is well recognized and therapeutic agents specifically inhibiting STAT3 signaling have been used to treat several types of cancers." (PMID 22723956, 2012). "STAT3 is a well-known oncogene and persistently activated in many human cancers, including all major carcinomas." (PMID 22615549, 2012). "Previous studies have reported other targets of DHC in cancer cells including NF-κB, STAT3, and induction of ER stress." (PMID 22359572, 2012). "For the nine added TF genes, seven of them were reported to take part in apoptosis in various types of cancer or diseases; these seven TFs are STAT3, ETS1, LEF1, STAT4, E2F3, ATF3, and HMGA2, which have not been annotated by GO yet." (PMID 22952919, 2012). "STAT3 is constitutively activated in a number of human cancer types such as lung cancer, breast cancer, multiple myeloma, and others." (PMID 23251591, 2012). "Recently, STAT3 has been considered as an important molecular target for cancer therapy due to its strong activation in various cancer cells including AML." (PMID 22493659, 2012). "Our observations confirm previous studies indicating that STAT3 inhibition downregulates survivin or Mcl-1 in various cancers." (PMID 22280969, 2012). "The study of STAT3 in cancer has revealed that JAK2/STAT3 was activated in starved Hela cells, with the activated STAT3 directly bound to IL-6 promoter to increase IL-6 mRNA and protein secretion." (PMID 22937006, 2012). "JAKs are the principal mediators of IL-6/gp130/STAT3 signaling and, in several cancer models, JAK inhibitors' anti-tumorigenic effects are mediated by STAT3." (PMID 23056499, 2012). "LLL12 is an optimized analog of LLL3, a novel small molecule allosteric STAT3 inhibitor that has been shown to inhibit proliferation and induce apoptosis in various cancer cell lines in vitro and in several mouse xenograft models, including OS." (PMID 23244668, 2012). "This study is the first to have examined in detail curcumin anti-cancer mechanistic role of JAK/STAT3 signaling in SCLC tumorigenesis and progression." (PMID 22662257, 2012). "ERp57 is also involved in the modulation of STAT3 signaling-regulated gene expression and has been reported to be upregulated in other types of cancer." (PMID 23118872, 2012). "Increasing evidence supports the application of STAT3 inhibitors, such as cucurbitacin, as therapeutic agents in treating various cancers." (PMID 22723956, 2012). "Targeting STAT3 as a potential cancer therapy has been extensively investigated, and recently new small-molecule inhibitors have been developed which show to inhibit IL-6-induced STAT3 activation and nuclear translocation in HCC cells." (PMID 22470194, 2012). "VEGF is another important regulator of angiogenesis and its expression in cancer cells has been shown to correlate with activation of STAT3." (PMID 22280969, 2012). "STAT3 inhibitors are already available and currently undergo testing in various animal cancer models." (PMID 23157946, 2012). "STAT3 is often constitutively active in many human cancer cells, including multiple myeloma, glioblastoma, leukemia, lymphoma, breast cancer, prostate cancer, lung cancer, and neck cancer." (PMID 22348037, 2012). "Transcriptional regulators of MMP-1 in cancer cells include STAT3 and members of the AP-1 family of transcription factors." (PMID 23217186, 2012). "Because STAT3 and FoxM1 are overexpressed in similar cancer types and coordinate similar cellular mechanisms, we investigated the relationship between FoxM1 and STAT3." (PMID 23110199, 2012). "STAT3 is a key transcription factor that mediates various cellular and organismal processes, such as cell growth, apoptosis, immune response and cancer." (PMID 23185365, 2012).
cancer (continued). "It has been reported that STAT3 participated in the development of a wide variety of human cancer, thus we detected phosphorylated STAT3 protein level in HeLa cells under the luteolin treatment condition by Western blot assay." (PMID 23145121, 2012). "In the present study, we found that EP exerts anti-cancer activity through the inhibition of angiogenesis by targeting the STAT3 signaling pathway in U266 cells in vitro and in vivo." (PMID 22260501, 2012). "These compounds can therefore serve as a valid molecular platform on which to optimize and develop improved STAT3-specific inhibitors for cancer therapy." (PMID 22899991, 2012). "Several reports have linked S1P signaling to the regulation of STAT3, including the recent study establishing that paracrine S1P signaling events are responsible for constitutive STAT3 signaling in cancer." (PMID 22606352, 2012). "As the oncogenic activation of tyrosine kinases is a common feature in cancers, we focused on the role of Tyr705 phosphorylation of STAT-3." (PMID 22937084, 2012). "JAKs are tyrosine kinases that mediate IL-6- dependent STAT3 activation, which has been shown to promote cancer progression in numerous examples of solid tumors." (PMID 23056499, 2012). "In many cancer cells, Stat3 signaling has been recognized as a pivotal pathway supporting survival and growth." (PMID 22279540, 2012). "The crucial role of STAT3 in cancer progression and tumorigenesis suggests that it is a promising molecular target for cancer treatment." (PMID 22179587, 2012). "Recently, small-molecule inhibitors of the STAT3 signaling have been reported to be effective anticancer agents in vitro and in vivo, indicating promising targeted therapies using molecules for cancers are emerging." (PMID 23166634, 2012). "STAT3 is a transcription factor that has been found to be constitutively activated in a number of human cancers." (PMID 23251591, 2012). "STAT3 is a transcription factor that regulates critical cell functions and plays important roles in several cancers." (PMID 23094050, 2012). "STAT3 target genes regulate many cellular processes, including proliferation and apoptosis, and constitutive activation of STAT3 has been observed in many human cancers." (PMID 22973309, 2012). "The activation pattern of STAT3 alters significantly in cancer cells, which is indicated by the abnormal expression of STAT3 and/or constitutive activation of the STAT3 signaling pathway." (PMID 23110625, 2012). "Signal Transducer and Activator of Transcription 3 (STAT3) is an oncogene, which promotes cell survival, proliferation, motility and progression in cancer cells." (PMID 22348037, 2012). "Transcription factor STAT3 is an important target protein that is involved in a multitude of human cancers." (PMID 23251591, 2012). "Luteolin bound to Hsp90 and induced its client proteins dissociate from Hsp90 and promoted degradation of some key antiapoptotic proteins such as activated STAT3 and Akt, and then induced apoptosis of carcinoma cells." (PMID 23145121, 2012). "Malignant tumors were 107.3 times more likely to express STAT3 (OR = 107.3, 95% CI: 20.24-569), and 7.5 times more likely to express pSTAT3 (OR = 7.5, 95% CI: 2.28-24.5) when benign or intermediate tumor is the reference." (PMID 21575192, 2011). "It is noteworthy that anti-cancer activity of BA is exerted by inhibiting angiogenesis via inhibition of binding of STAT3 and HIF-1α to the VEGF promoter in PC-3 cells." (PMID 21731766, 2011). "Currently, the main effort to target constitutive STAT3 signalling is only focused on the bulk of cancer cells." (PMID 21694723, 2011). "Mechanistic characterization revealed that NSC-743380 suppressed the phosphorylation of C-terminal domain of RNA polymerase II, induced JNK activation, inhibited JAK2/STAT3 phosphorylation and suppressed cyclin D1 expression in sensitive human cancer cells." (PMID 22174819, 2011).
cancer (continued). "Recent studies demonstrate the blockade of STAT3 expression in human cancer cells that suppresses the in vitro proliferation of cancer cells and the in vivo tumorigenicity." (PMID 22933956, 2011). "Resveratrol possesses multiple molecular effects on cancer cells in dose-dependent fashion and STAT3 signaling is one of its molecular targets." (PMID 22096581, 2011). "Our results indicate that knock-down of Src, and its downstream signaling partners STAT3 and cMyc, using siRNA in the human cancer cell line MDA-MB-435S, have a dramatic effect on its neoplastic properties." (PMID 21541295, 2011). "Although this signallingpathway is finely regulated to guarantee the physiological response,hyper-activation of STATs has often been observed in a number of pathologies,especially that of STAT3 in cancer and in some inflammatory diseases." (PMID 21625597, 2011). "The persistent activation of STAT3 helps the cancer development, and a high expression of STAT3 also indicates a poor prognosis of the cancer." (PMID 22933956, 2011). "STAT3 activation has also been observed in muscle in other experimental models of cancer cachexia with high IL-6, namely ApcMin/+ mice." (PMID 21799891, 2011). "Thirty seven of the 46 malignant tumors showed intense STAT3 expression in the cytoplasm whereas the remaining 9 tissues showed moderate and mild cytoplasmic positivity." (PMID 21575192, 2011). "Sesquiterpene lactone parthenolide and curcumin are cytotoxic to cancer stem cells and target the cells by inhibiting the activity of NF-κB and STAT3." (PMID 21779382, 2011). "STAT3, originally identified as an important regulator of lymphocyte interferon-mediated gene transcription, is constitutively activated in many cancers." (PMID 21304528, 2011). "Lastly, many transcription factors such as NF-κB, STAT3 and the adaptor protein MyD88, which are all key to the innate inflammatory response, are also essential in certain kinds of cancers." (PMID 22136659, 2011). "Previous studies have shown that the oncogenic STAT-3 protein was constitutively activated in many human cancers." (PMID 21991388, 2011). "The intermediate tumors expressed 52% nuclear expression for STAT3 while this was 85% in malignant tumors." (PMID 21575192, 2011). "Constitutive activation of STAT3 has been documented in ovarian, breast, colon, prostate, and several other types of cancer." (PMID 21575192, 2011). "Stat3 has increasingly been shown to play a role in migration and invasion of both normal and cancer cells." (PMID 22140473, 2011). "It has been reported that GRIM-19 can suppress transcriptional activity of STAT3 through protein-protein interaction, and inhibit cancer growth." (PMID 21765936, 2011). "These in vivo data clearly show that activated STAT3 in monocytes can promote cancer cells growth in a paracrine dependent manner." (PMID 22136659, 2011). "Our findings show that IL-6 apparently mediates both the hepatic and skeletal muscle acute phase response through STAT3 activation in cancer, thereby positioning the IL-6/STAT3 pathway as a potentially important target to reduce skeletal muscle wasting." (PMID 21799891, 2011). "In subsequent work, FLLL32 was shown to promote apoptosis in multiple human cancer cell lines, inducing downregulation of STAT3 phosphorylation and DNA binding." (PMID 21443800, 2011). "The inhibition of the STAT3 signaling pathway in cancer cells, using antisense oligonucleotides, RNA interference and dominant-negative STAT3, has been shown to cause decreased cellular growth and induce apoptosis." (PMID 21526200, 2011). "The constitutive activation of the STAT3 and Bcl-2 pathways is frequently observed in several cancer cell lines, including MM cells." (PMID 22177381, 2011). "In cancer, STAT3 and NF-κB have been shown to cooperate in promoting cell growth by interacting at different levels of their activating pathways." (PMID 21486470, 2011).
cancer (continued). "Since aberrant activation of STAT3 plays a critical role in the development of human cancers, including MM, numerous studies have tried to identify novel anticancer strategies/agents targeting STAT3." (PMID 21679466, 2011). "Stat3 activity in these cancer cells has been shown to depend on autocrine activation of EGFR by secreted TGFα." (PMID 21264347, 2011). "The present study uses both ALDH and CD133 together as markers for colorectal stem cells and examines the role of the STAT3 pathway in these cancer stem cells." (PMID 21694723, 2011). "NF-κB and STAT3 regulate numerous genes involved in inflammation and growth transformation and their persistent activation is observed in many cancers." (PMID 21291541, 2011). "The transcription factor, STAT3, has been found constitutively activated in a wide variety of cancers and in recent years it has become an attractive therapeutic target." (PMID 21526200, 2011). "In contrast, inhibition of the STAT-3 signaling pathway suppressed cancer cell invasion in various cancers." (PMID 21991388, 2011). "Constitutive activation of Stat3 has been observed in a number of human cancers and cancer cell lines." (PMID 21595927, 2011). "Constitutive activation of STAT3 provides cancer cells with growth and survival advantages by activating multiple pathways within the cell, involving a broad range of genes." (PMID 22046235, 2011). "Lithium strongly inhibited STAT3 (signal transducer and activator of transcription 3) activation, a messenger system known to promote astrogliogenesis and cancer." (PMID 21931595, 2011). "LLL12 did not induce apoptosis in normal human hepatocyte and lung fibroblast cell lines, indicating that its toxicity is confined to cancer cells which express p-STAT3." (PMID 21526200, 2011). "On the other hand, IL-6 promotes cancer cell proliferation while also inhibits apoptosis of cancer cells through activation of signal transducer and activator of transcription 3 (Stat3)." (PMID 22162712, 2011). "Inhibition of STAT3 has been shown to reduce cell viability and to promote apoptosis in various cancer models." (PMID 21730976, 2011). "NF-κB and STAT-3 signaling are proposed to serve as major regulatory systems linking inflammation to cancer." (PMID 22022583, 2011). "It has been reported that constitutive activation of STAT3 is common in many human and murine cancer cells, and leads to cellular transformation." (PMID 21679466, 2011). "JAK/STAT3 activation also increases SOCS (suppressors of cytokine signalling), abnormalities of which cause cancer." (PMID 21931595, 2011). "STAT3 is generally regarded as a requirement for Src-mediated cell transformation as shown in many carcinomas." (PMID 22174695, 2011). "Now, low and behold, STAT3 appears to be involved with the earliest recognized metabolic abnormality of cancer cells, energy derivation through glycolysis." (PMID 21149895, 2010). "Of 50 cancer biopsies examined for immunohistochemical analysis of STAT3, 42 were found positive for STAT3 and out of these, 71% had either moderate or high STAT3 expression and had variable degree of nuclear positivity [and]." (PMID 20977777, 2010). "These cytoplasmic tyrosine kinases, often in conjunction with Jaks, are likely to mediate Stat3 activation subsequent to many other cancer-initiating, toxic insults, including UV-radiation, stress, and smoke." (PMID 20478049, 2010). "The first description of STAT3 in 1994 raised suspicion in the direction of cancer because IL-6 and EGF, already recognized to have cancer connections, were the originally recognized ligands that activated the STAT3 homodimer." (PMID 21149895, 2010). "This study was designed to determine the role of Jak2/Stat3 pathway in the regulation of IL-6 autocrine production in cancer cells." (PMID 21122157, 2010). "Instead, the IL-6 downstream signal pathways, including Jak2/Stat3, co-cooperated to control the IL-6 autocrine production in the cancer cells we tested." (PMID 21122157, 2010).
cancer (continued). "Present study has been designed to investigate expression and activation of STAT3 in cervical precancer and cancer in relation to HPV infection during cervical carcinogenesis." (PMID 20977777, 2010). "Elevated level of pSTAT3 in MDSCC and PDSCC were also corroborated with intense nuclear positivity of STAT3 in histologically-advanced cancer tissues and was found in as high as 78% and 88% of cancer cells in MDSCC and PDSCC respectively." (PMID 20977777, 2010). "Constitutive activation of Stat3 in epithelial cancers and cancer derived cell lines is frequently due to aberrant autocrine or paracrine IL-6 signaling." (PMID 20929542, 2010). "Several reports have shown inhibition of Stat3 pathways in cancer cells, resulting in a dramatic increase of apoptosis." (PMID 20459702, 2010). "In that the PPARγ agonist CDDO-Me inactivates Src and Stat3 in cancer cells, further investigation of the efficacy of various PPARγ ligands as anticancer agents is certainly warranted." (PMID 20204067, 2010). "It is puzzling why cancer cells should specifically become dependent on STAT3 for aerobic glycolysis, since most STAT3-activating oncogenic signals can also activate PI3K, a known mediator of this phenomenon." (PMID 21084727, 2010). "Further, we examined the expression and phosphorylation of STAT3 in cervical precancer and cancer tissues and compared with normal controls." (PMID 20977777, 2010). "Targeting the STAT3 pathway directly should be a promising and novel form of treatment for these human cancers." (PMID 20712901, 2010). "IL-6 activates a feed-forward loop leading to increased STAT3 activation in cancer and inflammatory cells, where STAT3 promotes polarization of innate immunity towards immuno-suppressive alternate activation." (PMID 21059221, 2010). "Curcumin is known to inhibit several targets closely associated with cancer cell proliferation, in particular JAK2/STAT3 pathway." (PMID 20712901, 2010). "Expression and activity of STAT3 were found to change as a function of severity of cervical lesions from precancer to cancer." (PMID 20977777, 2010). "In AS2 derived cells, resistance to paclitaxel was positively correlated with Stat3 activation status and the expression of IL-6, which is commonly secreted in drug resistant cancer cells." (PMID 21122157, 2010). "STAT3 which is phosphorylated by numerous cytokines, growth factors and oncogenetic proteins, is constitutively phosphorylated in many human cancer tissues and cell lines." (PMID 20553623, 2010). "Aberrant expression/activation of STAT3 has been observed in a wide number of human cancer cell lines and primary tumors including blood cancers and solid tumors and has been shown to be associated with the poor prognosis in various types of malignancies." (PMID 20977777, 2010). "Signal transducer and activator of transcription-3 has been reported to be constitutively activated in various types of malignant tumours, and increased STAT3 activation has been recognised as an indicator of poor prognosis." (PMID 20461084, 2010). "The cancers in which miR-21 is overexpressed contain constitutively activated Stat3 for survival or growth." (PMID 20204067, 2010). "These insights provide clues to the judicious interference of the gp130/Stat3 signaling cascade in therapeutically targeting cancer." (PMID 20478049, 2010). "The expression of STAT3 and its phosphorylated forms was found to increase as a function of severity of the cervical lesions from precancer to cancer stages." (PMID 20977777, 2010). "The STAT3 is also known to be involved in regulating cancer metastasis, and activation of STAT3 correlates with lymph node and distant metastasis." (PMID 20461084, 2010). "Recently, accumulating evidence has indicated that abnormalities in the Stat3 pathway are involved in the oncogenesis of several cancers." (PMID 20482858, 2010).